FAM50A (family with sequence similarity 50 member A)
Description:
Probably involved in the regulation of pre-mRNA splicing.
Synonyms: DXS9928E; HXC26; XAP5; HXC-26; 9F; MRXSA
Tractability: Small molecule: a structure with a bound ligand is known. PROTAC: UniProt records ubiquitination sites on it; ubiquitination databases record sites on it; its protein half-life has been measured.
Gene: Protein-coding gene on chromosome X (154,444,103 to 154,450,654, forward strand). Ensembl gene ENSG00000071859.
Subcellular location: Nucleus
Subcellular location (Human Protein Atlas): Nucleoplasm
Pathways (Reactome):
Metabolism of RNA: mRNA Splicing - Major Pathway
Gene Ontology:
Molecular function: protein binding; RNA binding
Biological process: regulation of RNA splicing; chromatin organization; spermatogenesis
Cellular component: nucleoplasm; nucleus
Homologues: Orthologues: macaque FAM50A (99% identical), rabbit FAM50A (99% identical), rat Fam50a (99% identical), mouse Fam50a (98% identical), guinea pig FAM50A (97% identical), dog FAM50A (97% identical), chimpanzee FAM50A (96% identical), pig FAM50A (95% identical), zebrafish fam50a (86% identical), tropical clawed frog fam50a (83% identical), Drosophila melanogaster CG12259 (65% identical), Caenorhabditis elegans C47E8.4 (47% identical). Paralogues in human: FAM50B (74% identical).
Diseases named in the same sentence as FAM50A in open-access papers:
FAM50A is named in the same sentence as 20 diseases in open-access papers, as found by Europe PMC text mining. Sharing a sentence is not in itself a finding about the gene and the disease. The quoted sentences say what the papers report.
breast tumors (2 papers, 2012 to 2019). "The most significant differences in expression pattern were revealed for RAD50 and LGALS3BP in cancer cells of different histological types of breast cancer and for PABPC4 and FAM50A antigens in immune cells infiltrating breast tumors." (PMID 23181716, 2012). "The most significant differences in expression pattern were revealed for RAD50 and LGALS3BP in different histological types of breast cancer and for PABPC4 and FAM50A antigens in immune cells infiltrating breast tumors." (PMID 23181716, 2012). "In primary human breast tumors, the most common ITGB1 isoform 1 A was positively correlated to Suppressor-SFs such as DDX3X and DHX9 while being negatively correlated to Enhancer-SFs such as CCDC12 and FAM50A." (PMID 30940821, 2019). "Moreover, antigens FAM50A and PABPC4 are intriguing targets for investigation of the features of the immune response in patients with highly infiltrating breast tumors including MBC, which despite anaplastic features has favorable prognosis." (PMID 23181716, 2012).
Intellectual disability (2 papers, 2024). "Most recently, syndromic intellectual disability has been described as an emerging phenotype linking variants in 2 genes, PUF60 and FAM50A, which encode spliceosomal components of the U2 snRNP and the C-stage spliceosome complexes, respectively." (PMID 37962958, 2024). "Through pull-down assay and mass spectrometry analysis using FAM50A as bait, we identified RFC3 and RFC5 as components of the FAM50A complex, suggesting potential roles for RFC genes in developmental disorders, including intellectual disability." (PMID 39368701, 2024).
medullary breast carcinoma (2 papers, 2012 to 2023). An infiltrating breast carcinoma with a relatively favorable prognosis. "In the study of tumors, researchers found the pro-cancer role of FAM50A in medullary breast carcinoma, chronic lymphoblastic leukemia and other tumors." (PMID 36834630, 2023). "In current study we analyzed six previously identified medullary breast carcinoma autoantigens including LGALS3BP, RAD50, FAM50A, RBPJ, PABPC4, LRRFIP1 with cancer restricted serological profile in different histological types of breast cancer." (PMID 23181716, 2012).
bladder urothelial carcinoma (1 paper, 2025). "Analysis revealed that FAM50A was significantly overexpressed in various tumors, including bladder urothelial carcinoma, colon cancer, rectal cancer, and other common tumor types (P < 0.05)." (PMID 39999107, 2025).
breast carcinoma (1 paper, 2012). "This pilot study made possible to select 4 antigens LGALS3BP, RAD50, PABPC4, and FAM50A as promising candidates for more comprehensive research as potential molecular markers for breast cancer diagnostics and therapy." (PMID 23181716, 2012). "Thus, during this study we described for the first time expression patterns of 6 potential MBC-associated antigens, including LGALS3BP, RAD50, FAM50A, RBPJ, PABPC4, LRRFIP1 in different histological types of breast carcinomas and non-cancerous breast tissues by immunohistochemical analysis." (PMID 23181716, 2012).
endometrial disorder (1 paper, 2018). A non-neoplastic or neoplastic disorder that affects the endometrium. "No relevant studies focus on the relationship of Entpd1, Fam50a, and Brms1 to endometrial disorders, and further studies are needed." (PMID 30322386, 2018).
rectal cancer (1 paper, 2025). A primary or metastatic malignant neoplasm that affects the rectum. "Since FAM50A was highly expressed in both colon and rectal cancer, and given that CRC is our long-term research focus, this gene was selected for further detailed investigation." (PMID 39999107, 2025).
viral infection (1 paper, 2025). "Unlike well-characterized spliceosomal components, FAM50A remains largely unexplored in both cancer and viral infection." (PMID 40503897, 2025).
X-linked intellectual disability syndrome (1 paper, 2024). "Previously, we identified RFC3 and RFC5 as interacting proteins to FAM50A, the deficiency of which causes an X-linked intellectual disability syndrome." (PMID 39368701, 2024).
tumor (7 papers, 2012 to 2025). "Loss of FAM50A markedly suppressed tumor progression in KMM-derived xenografts." (PMID 40503897, 2025). "FAM50A/FAM50B are particularly notable among our collection of genetic interactions because ~4% of cancers profiled by the TCGA show loss of FAM50B expression (0–10% across tumour categories), thus highlighting the FAM50A/FAM50B axis as a potential therapeutic target." (PMID 33637726, 2021). "To evaluate its role in tumorigenesis, we examined tumor growth in nude mice using FAM50A knockout cells." (PMID 40503897, 2025). "The knockdown of Fam50a decreased the luciferase activity of these cells in Runx2-expressed tumor cells." (PMID 37150786, 2023). "The results of multivariate COX regression analysis indicate that FAM50A expression and tumor status were independent predictors of OS for HCC patients." (PMID 36834630, 2023). "We identified the role of FAM50A in the tumor immune microenvironment (TIME) and immunotherapy efficacy in HCC." (PMID 36834630, 2023). "Based on univariate COX regression analysis, we found that the pathological stage, T stage, M stage, tumor status and FAM50A expression were significantly correlated with the overall survival (OS) of patients with HCC." (PMID 36834630, 2023). "Silencing of FAM50B occurs across a range of tumour types and in this context disruption of FAM50A reduces cellular fitness whilst promoting micronucleus formation and extensive perturbation of transcriptional programmes." (PMID 33637726, 2021). "FAM50A protein predominantly was distributed in nucleus and cytoplasm of cancer cells of all tumor samples with preferentially moderate (2+) and weak (1+) positive staining respectively." (PMID 23181716, 2012). "This means the elevated expression of FAM50A promotes tumor growth in vivo." (PMID 36834630, 2023). "Given that E-cadherin inhibited tumor cell invasion significantly more effectively in the SynG2/M phase than in the SynG1 and SynS phases, we wonder if its overexpression specifically deactivates the Fam50a/Runx2-MMP13 axis." (PMID 37150786, 2023). "It appears that the high expression of FAM50A can promote tumor proliferation." (PMID 36834630, 2023). "We investigated whether the function of E-cadherin against tumor cell migration and invasion via the Fam50a/Runx2-MMP13 axis had any effect on tumor cell invasion." (PMID 37150786, 2023). "FAM50A promoted tumor infiltration or metastasis, and it reduced the sensitivity to lenvatinib." (PMID 36834630, 2023). "Thus, despite efficient editing at the gRNA binding site all resistant tumours were predicted to have retained some FAM50A activity." (PMID 33637726, 2021). "Interestingly, overexpression of Fam50a could reduce the inhibitory effects of E-cadherin against tumor invasion, while knockdown of Fam50a could recover the tumor invasion inhibitory effects for loss of E-cadherin." (PMID 37150786, 2023). "These 6 tumor-exclusive proteins detected in every single sample comprised MARCKSL1, IKBIP, COPZ1, TIMP1, FAM50A and DPM3." (PMID 39681068, 2024). "This suggests that the downregulation of FAM50A suppressed the development of EMT, which may inhibit tumor infiltration or metastasis." (PMID 36834630, 2023).
cancer (6 papers, 2012 to 2025). A tumor composed of atypical neoplastic, often pleomorphic cells that invade other tissues. "A closer examination of the affected transcripts revealed genes with established roles in cancer development, particularly those downregulated in FAM50A-deficient KMM cells, which may be key mediators of its function in KSHV-induced oncogenesis." (PMID 40503897, 2025). "The expression level of FAM50A varies across different tissues and tumors in the human body, as revealed by pan-cancer analysis of public databases." (PMID 39999107, 2025). "Emerging evidence suggests that FAM50A functions as a proto-oncogene, contributing to the progression of multiple types of cancer." (PMID 40503897, 2025). "In studies of cancer, FAM50A has been demonstrated to participate in the progression of myeloid breast cancer and chronic lymphocytic leukemia." (PMID 36834630, 2023). "Removing FAM50A disrupted splicing, weakening cancer-promoting signals." (PMID 40503897, 2025). "However, despite its clinical significance, the precise role of FAM50A in oncogenesis and cancer progression remains largely unexplored." (PMID 40503897, 2025). "Targeting FAM50A may offer new therapeutic opportunities for KSHV-associated malignancies and potentially other cancers dependent on aberrant splicing." (PMID 40503897, 2025). "In conclusion, we clarified the pro-cancer role of FAM50A in HCC from multiple perspectives." (PMID 36834630, 2023). "All these suggest that FAM50A acts as a cancer-inducer in HCC." (PMID 36834630, 2023). "Our studies reveal the fitness effects of FAM50A/FAM50B in cancer cells." (PMID 33637726, 2021). "Moreover, PABPC4 showed more intensive cytoplasmic staining of immune cells compared with cancer and normal cells, as well as nuclear antigen with unknown function FAM50A." (PMID 23181716, 2012). "A research has revealed that when FAM50A was knocked down, it could lead to DNA damage, elicit the expression of interferon beta and interleukin-6, and inhibit the proliferation, invasion and migration of cancer cells, which is basically in accordance with our results in this study." (PMID 39999107, 2025). "Elevated FAM50A expression correlates with poor prognosis and negative response to immunotherapy across several cancer types (22, –, 24)." (PMID 40503897, 2025). "Using ROC curve analysis of scores in normal and cancer tissues, 3.5 was determined as the cut-off value for distinguishing patients with CRC revealing a high (95 patients, 65.5%) or low (50 patients, 34.5%) level of FAM50A expression." (PMID 39999107, 2025). "During the study of tumors, the researchers found that, in medullary breast cancer tissue samples with abundant lymphocytic infiltration, the expression of FAM50A in immune cells was significantly higher than that in both cancer and non-cancer cells." (PMID 36834630, 2023). "Analysis of FAM50A protein expression revealed that more than 50% of cells were positively stained in cancer and non-cancerous tissue sets." (PMID 23181716, 2012). "According to our findings FAM50A protein is expressed both in nucleus and cytoplasm in the most cells of cancer and non-cancerous breast tissues without any significant differences." (PMID 23181716, 2012).
neurodevelopmental disorder (2 papers, 2021 to 2024). A behavioral and cognitive disorder with onset during the developmental period that involves impaired or aberrant development of intellectual, motor, or social functions. "However, the specific role of the interaction between RFC proteins and FAM50A, a spliceosomal protein, in relation to neurodevelopmental disorders remains unclear." (PMID 39368701, 2024).
genetic disorders (1 paper, 2020). "Among genes with significantly altered gene expression in fam50a KO, some cause clinically similar genetic disorders." (PMID 32703943, 2020).
FAM50A also shares sentences with these, for which no sentence is quoted: Armfield syndrome (1 paper); ciliopathies (1); colon cancer (1); colorectal cancer (1); Infertility (1); invasive carcinoma (1); X-linked intellectual disability (1).